H19 (H19 imprinted maternally expressed transcript)
Diseases named in the same sentence as H19 in open-access papers (continued):
Sharing a sentence is not in itself a finding about the gene and the disease.
tumor (continued). "In BC, the aberrant expression of H19 is associated with the proliferation and progression of the tumor by diverse underlying molecular mechanisms, including interaction with c-myc, encoding microRNA-675, and competition for the regulation of endogenous RNAs." (PMID 34885213, 2021). "All three had a confirmed predisposition, i.e., a germline WT1-mutation (n = 2) and hypermethylation of the H19-locus in healthy kidney and tumor tissue only (n = 1)." (PMID 34884260, 2021). "Nevertheless, we observed that the inhibition of H19 was associated with a strongly reduced cell viability, migration, invasion and tumor growth." (PMID 33669381, 2021). "Expression level of H19 was significantly correlated with tumor grade and IDH1(R132) mutation status (p < 0.05)." (PMID 34081618, 2021). "The in vivo result showed that compared to the Con, tumor growth was remarkably suppressed with loss expression of H19." (PMID 32485786, 2020). "In FTC, H19 was revealed as the prognostic factor negatively associated with tumor size, distant metastasis and vascular invasion." (PMID 33158279, 2020). "H19 is a maternally expressed allele, non-coding RNA, and its function is still unclear, although it has been postulated a tumor suppressor role." (PMID 33101381, 2020). "We examined the associations between the H19 mRNA level and the pathologic tumor and nodal stage according to the baseline PSA level by accessing The Cancer Genome Atlas (TCGA) database." (PMID 32878251, 2020). "Especially, H19 has been reported to up-regulated in CRC tissues compared with non-tumor tissues and H19 overexpression is closely associated with poor survival of CRC patients." (PMID 33267897, 2020). "Using the Kaplan-Meier method, abnormal H19 methylation (defined as a methylation index > 60%) was strongly associated with an increased risk of tumour development (34.6% vs. 4.2%, hazard ratio 10, p < 0.0001)." (PMID 32642955, 2020). "In PTC, H19 was shown to be inversely associated with tumor size, pathological lateral node metastasis, extrathyroid extension, histological aggressive type and poorer disease-free survival." (PMID 33158279, 2020). "Transmission of exosomal H19 from CAFs to the neighboring cells is strongly associated with tumor development and resistance to oxaliplatin." (PMID 32957712, 2020). "Over-expression of HOTS in cancer cell lines inhibited their growth and HOTS expression was absent in Wilms’ tumors that showed loss of heterozygosity or LOI at IGF-II/H19 and, thus, appeared to function as a tumor suppressor." (PMID 31590432, 2019). "Cox regression and correlation analysis showed that H19 and some other competing endogenous RNAs in the network are associated with poor prognosis and clinical parameters such as tumor grade and metastasis." (PMID 31164794, 2019). "Taken together with the notion that a single-nucleotide polymorphism (SNP) of H19 is linked to increased risk and tumor size of fibroids, our results suggest a critical role of H19 in the pathogenesis of UFs." (PMID 31089260, 2019). "With regard to other clinical parameters, we found that H19 upregulation is linked to tumor grade, lymphatic invasion, metastasis, and TNM stage." (PMID 31164794, 2019). "MiR-675, which is known as one of the most important transcripts in the H19 locus, is located at exon 1 and implicated in the carcinogenesis and tumor invasiveness." (PMID 31772651, 2019). "The oncogenic potential of H19 was confirmed by reduction in tumor volume caused by siRNA-H19 transfected Hep3b cells." (PMID 30158867, 2018). "Overexpression of H19 is associated with tumor grade, differentiation, neck lymph node metastasis, clinical stage, and OS." (PMID 29416703, 2018). "H19 acts mainly through two ways: first, miR-675, encoded by the first exon of H19, regulates the relevant tumor suppressor genes; second, the total length of H19 combines with microRNAs or related proteins to regulate their functions." (PMID 29449695, 2018).
tumor (continued). "H19 is linked to HCC tumor with inflammatory conditions including viral hepatitis, alcoholic and NASH." (PMID 30158867, 2018). "In some cases, the H19 locus has been suggested to act as a tumour suppressor, and mice bearing a mutation in the Apc gene are murine models for colorectal cancer." (PMID 29972883, 2018). "The data from independent patient cohorts showed a clear downregulation of H19 in HCC as a strongly inflammation-associated tumor type." (PMID 31225433, 2017). "H19 is significantly overexpressed in CD133-positive GBM cells, and higher H19 expression levels are associated with increased tumor growth." (PMID 28293170, 2017). "In fact, H19 deficient mice demonstrated increased tumor development by the carcinogen diethylnitrosamine (DEN) with tumors that showed increased cell proliferation as well as dysplastic lesions characteristic for liver carcinogenesis." (PMID 31223144, 2017). "Further analysis revealed that the deregulated lncRNAs in ESCC included many well-known tumor-associated lncRNAs, such as H19, TUG1 and SOX2OT, which have been reported to contribute to tumorigenicity in other cancers." (PMID 28854977, 2017). "It suggested that the group of high H19 expression had a higher risk of deep tumor invasion (T2 stage or more) than those of low H19 expression." (PMID 27738631, 2016). "Other H19-modulated genes are implicated in the survival/apoptotic decision in hypoxic stress, while others are implicated in tumor progression migration, invasion and metastasis." (PMID 26623562, 2016). "A total of four studies reported the association between lncRNA H19 expression and tumor invasion depth." (PMID 27738631, 2016). "In summary, the high expression of lncRNA H19 was linked with poorly differentiated grade, deep tumor invasion, and lymph node metastasis, suggesting it as a biomarker of poor prognosis for patients with digestive system cancers." (PMID 27738631, 2016). "Studies have suggested that H19 possesses tumor-suppressor functions and have implicated chromatin insulator protein CCCTC-binding factor (CTCF) in methylating the promoter region of the H19 gene." (PMID 26989421, 2016). "The increase in HGF level after partial hepatectomy results in rapid hepatocyte proliferation, and also causes the overexpression of H19 in the liver tissue and tumor, which explains rapid growth of liver metastases after partial liver resection." (PMID 26623562, 2016). "The imprinted H19 gene encodes a lncRNA implicated as having both oncogenic and tumor suppression properties." (PMID 26415227, 2015). "While the paternally expressed IGF2 encodes a member of the insulin family of polypeptide growth factors, which are involved in growth and development, the maternally expressed H19 encodes a non-coding RNA, and functions as a tumor suppressor." (PMID 29963333, 2014). "One-way ANOVA analysis showed that H19 expression levels were significantly associated with tumor grade (P<0.0001 for both Rembrandt data and GSE16011 data), which was similar with the CGGA data." (PMID 24466011, 2014). "Emerging evidence showed that erasure of H19 imprinting and subsequent high expression level of H19 was associated with tumor growth, metastasis and invasion of several types of cancer." (PMID 25387074, 2014). "H19 gene was also shown to play an important role in tumor growth; its expression caused differential expression of other genes." (PMID 21052499, 2010). "Our results indicate a direct effect of H19 RNA on tumor growth, and a strong association between hypoxia and H19 levels." (PMID 17786216, 2007). "A reduced H19 expression was detected, warranting long-term follow-up to monitor tumor risk." (PMID 41262921, 2025).
tumor (continued). "Furthermore, H19 modifies the genes of signaling pathways linked to metastasis, improving tumor cells’ capacity to spread to different organs." (PMID 41013839, 2025). "This deeper molecular understanding enables a more precise classification of patients based on the underlying tumor dissemination program regulated by the hypoxia and estrogen stimuli on the H19/cell adhesion molecules circuitry and provides a rationale for novel diagnostic strategies." (PMID 39457633, 2024). "PTCSC3 (Papillary Thyroid Carcinoma Susceptibility Candidate 3), found to be a tumor suppressor in numerous cancers, may serve as an upstream inhibitor of H19, regulating cell proliferation in TNBC cells." (PMID 38505593, 2024). "In HepG2 cells, H19 expression was induced by tumor-associated macrophages, suggesting that inflammation might regulate H19 expression." (PMID 38203767, 2024). "Furthermore, structural alterations (rearrangements and deletions) in tumor DNA at 11p15 are a frequent finding and can cause loss of imprinted H19 tumor suppressor gene and overexpression of the IGF2 oncogene." (PMID 38108848, 2024). "lncRNA H19 was found to be transferred from carcinoma‐associated fibroblasts (CAFs) to tumour cells through exosomes, and exosome‐derived lncRNA H19 could activate the β‐catenin pathway as a ceRNA sponge for miR‐141 in CRC and AOM/DSS‐treated CAC mouse model." (PMID 37138536, 2023). "An important aspect of BWS diagnostics is childhood tumor prediction since imprinting aberrations in the imprinting center IC1 (also called the H19/IGF2 Differentially Methylated Region, DMR) are associated with high tumor risk whilst those in IC2 (KCNQ1OT1 DMR) are not." (PMID 35860466, 2022). "H19 is linked with diverse cancer types and has both tumor promoter and suppressive roles." (PMID 35723379, 2022). "However, in prostate cancer, the opposite phenomenon has been observed, that is, H19 inhibits tumor metastasis, mainly by encoding miR‐675 to mediate the down‐regulation of TGFBI." (PMID 34977870, 2021). "High expression of H19 was associated with tumor diameter and TNM stage." (PMID 33842553, 2021). "A recent study found that H19 could be induced by M2‐type tumor‐associated macrophages, which was followed by activation of downstream ceRNA targets." (PMID 34598322, 2021). "Interestingly, lncRNA H19 knockdown in oral CAFs suppressed tumor growth in vivo, indicating that lncRNA H19 expressed by oral CAFs was associated with the ability of cancer cells to sustain proliferation." (PMID 33762576, 2021). "Besides, a prominently higher tumor T status was found in subjects with LncRNA H19 SNP rs2107425 T allele (CT + TT) (stage III or IV, p = 0.007) compared to EGFR wild-type LADC individuals with LncRNA CC allele in EGFR wild-type patients." (PMID 33799753, 2021). "Additionally, overexpression of H19 is associated with poor prognosis and clinical parameters such as tumor grade, lymphatic invasion, metastasis, and TNM stage." (PMID 34977037, 2021). "Although H19-mediated tumor suppression has been demonstrated in LFS-associated osteosarcomagenesis, the underlying mechanisms of its tumor suppressor activity remain unclear." (PMID 33519915, 2020). "Interestingly, a recent study showed that tumor-associated macrophages highly express H19 and thereby promote HCC aggressiveness." (PMID 32429417, 2020). "A study using tissue samples from patients with perihilar, distal, or intrahepatic CCA (iCCA) has represented that H19 expression is upregulated in CCA tissues compared to corresponding non-tumor tissues, and expression levels of H19 are associated with poor survival rates of patients." (PMID 32154257, 2020).
tumor (continued). "Interestingly H19 expression was induced in HepG2 cells by tumor-associated macrophages suggesting a potential role of inflammation in regulating H19 expression." (PMID 32429062, 2020). "Since persistent activation of H19 might be a key factor in age-related tumorigenesis, H19 might similarly contribute to tumor growth and inflammation associated with aging." (PMID 33193379, 2020). "Previous reports also suggested that reduced H19 expression was associated with tumor development." (PMID 32485786, 2020). "In addition, polymorphisms within the H19 gene in many ethnic populations have been related to the susceptibility to various tumor types, including bladder, gastric, colorectal, lung, breast, ovarian, liver, bone, and oral cancer." (PMID 31277475, 2019). "In another study, reduced lncRNA H19 expression in hepatocarcinogenesis tissues from patients is associated with the epithelial TGF-β gene signature while increased H19 expression promoted tumor metastasis in Hep3B cells." (PMID 31744193, 2019). "Low H19 expression was associated with large tumor size, vascular invasion, and distant metastasis." (PMID 31791180, 2019). "Aberrant expression of H19 has been associated with tumor progression." (PMID 31791180, 2019). "Long non-coding RNA (lncRNA) H19 has been implicated in tumor angiogenesis." (PMID 30948500, 2019). "Aberrant expression of long noncoding RNA H19 has been associated with tumour progression, but the underlying molecular tumourigenesis mechanisms remain largely unknown." (PMID 30397197, 2018). "H19 is transcribed exclusively from the maternal allele, and the gene also generates an oncofetal RNA that is expressed in the developing embryo and in certain types of tumor." (PMID 30410672, 2018). "Moreover, high expression of H19 is associated with tumor differentiation and tumor node metastasis (TNM) staging." (PMID 28108736, 2017). "We determined that the tumor growth was significantly inhibited in mice treated with lentivirus encoding H19 shRNA, compared to those treated with lentivirus encoding control shRNA, evidenced by significantly reduced weight of tumor mass (1.272 ± 0.213g vs 2.112 ± 0.273g, p < 0.01)." (PMID 26872375, 2016). "A literature search of the LncRNADisease database found that most of these pathways were previously associated with H19, confirming that H19 is an important regulator in many types of cancers and can therefore be used as a potential tumor marker for initial diagnosis and monitoring of therapies." (PMID 26424084, 2015). "Based on this property, we propose that this miRNA-associated feature of H19 may therefore enhance the survival of circulating tumor cells." (PMID 24346158, 2014). "It has been implicated that H19 functions as a tumor suppressor." (PMID 23533668, 2013). "Furthermore, ectopic expression of the H19 gene in human embryonic tumour cell lines leads to loss of clonogenicity and reduced tumourigenicity in nude mice." (PMID 22662250, 2012). "H19 has been implicated as having both oncogenic and tumor suppression properties in cancer." (PMID 21489289, 2011). "We also crossed this mouse with a knockout of H19, a postulated imprinted modifier gene of Sdhd tumorigenesis, to evaluate if loss of these genes together would lead to the initiation or enhancement of tumor development." (PMID 19956719, 2009). "Next, we questioned whether H19 RNA is a tumor-associated gene product or whether it is potentially harboring an oncogenic potential by itself." (PMID 17786216, 2007). "In this respect, our data in RASFs differ from reported studies of tumor cell lines in which high levels of H19 could be linked to oncogenic properties such as epithelial-mesenchymal transition (EMT) associated with invasive, migratory and metastatic properties." (PMID 40118917, 2025). "However, the appearance of genetic variations may cause abnormal expression of H19, which leads to the disruption of gene regulation mechanisms and increases the risk of tumor occurrence." (PMID 39267845, 2024).
tumor (continued). "H19 is overexpressed in various cancerous tissues andhas been shown to be associated with carcinogenesis, cellproliferation and differentiation, metastasis, poor prognosis,and tumor growth in various cancers, while normal expressionof H19 has been shown in healthy individuals." (PMID 36680478, 2023). "In addition, overexpression of H19 in GC cells and tissues has been linked to tumor progression." (PMID 34987543, 2021). "To test whether the H19 rs2839698 polymorphism could has effects on disease progression; we then analyze the association between rs2839698 genotypes and the tumor size, clinical stage and tumor grade of RCC in the patient group." (PMID 32509581, 2020). "Importantly, we unravelled the underlying molecular mechanism of H19-mediated tumour suppression." (PMID 30397197, 2018). "Our data showing that H19 overexpression suppresses 4E-BP1 phosphorylation is consistent with recent clinical findings that high 4E-BP1 phosphorylation levels are associated with poor prognosis in several tumour types, including breast, ovary and prostate tumours." (PMID 30397197, 2018). "Subsequent experiments implicated H19 may function as a tumor suppressor." (PMID 23711233, 2013). "Comprehensive cell-cell communication analysis showed that H19 + myoEpC orchestrated a signaling network with CAFs, immune cells, and endothelial cells, driving tumor progression and immune evasion." (PMID 41761191, 2026). "CONCLUSIONS: Our study provides the single-cell resolution map of ACCB from a representative case, highlighting the unique role of H19 + myoEpC in tumor progression and immune suppression." (PMID 41761191, 2026). "While several in vivo studies, despite their limitations, suggest that H19 acts as a tumor suppressor, various in vitro experiments, including ours, point to a possible oncogenic function for H19." (PMID 41521159, 2026). "It is conceivable that H19 indeed exerts opposing functional properties (tumor suppressive vs. oncogenic) in vivo compared to in vitro." (PMID 41521159, 2026). "In order to compare H19 expression from cell lines and tumor tissue samples, data from The Cancer Genome Atlas Program (TCGA) and the Genotype‐Tissue Expression (GTEx) project were analyzed using the online tool GEPIA." (PMID 41521159, 2026). "We extracted total RNA from mouse tumor tissues using TRIzol and analyzed the correlation between H19, hsa-miR-138-5p, hsa-miR-22-3p, and BMP2 mRNA levels using qPCR." (PMID 40297808, 2025). "Altered H19 expression has been observed in various cancers, affecting tumor growth, metastasis, and therapy resistance." (PMID 41009448, 2025). "For instance, H19 can promote angiogenesis and tumor growth, although it can have differing roles depending on the cancer context." (PMID 41154428, 2025). "The oncogenic role of H19 is now well recognized: aberrant H19 expression correlates with tumor growth, proliferation, invasion, metastasis, treatment resistance, and poor patient outcomes in several cancers." (PMID 40649905, 2025). "This suggests that H19 is a key downstream regulatory factor in the anti-tumor process involving high FAM117A expression and low PIGU expression." (PMID 41542087, 2025). "SNHG6 was expressed at the tumor edge and in the pseudopalisading regions around necrosis, but most lncRNAs (Pvt1, SNHG12, H19, Neat1, Malat1, Mir17hg and Ftx) were expressed around the necrotic tumor regions." (PMID 40527978, 2025). "It is a plasmid-based DNA therapy that targets the H19 lncRNA promoter, leading to the expression of diphtheria toxin A selectively in H19-expressing tumor cells." (PMID 40781643, 2025). "H19 can control the production of invasive factors like MMPs, which aid in the breakdown of the extracellular matrix and promote the migration of tumor cells." (PMID 41013839, 2025).